ALB (albumin)
Diseases named in the same sentence as ALB in open-access papers (continued):
Sharing a sentence is not in itself a finding about the gene and the disease.
diabetes (continued). "Therefore, glucose availability seems to plays an important role in albumin-enhanced C. glabrata pathogenicity, which is especially relevant when taking into account the high incidence of VVC caused by C. glabrata in diabetes mellitus patients." (PMID 34710198, 2021). "Thus, the present study aimed to evaluated the association between serum albumin and DPN, defined as vibration perception threshold (VPT) values ≥ 25 V and/or inability to feel the monofilament, in Chinese patients with type 2 diabetes mellitus (T2DM)." (PMID 34526116, 2021). "Compared with the concordant group, patients in the non-albumin-predominant group were older with lower BMI besides having a higher prevalence of diabetes, hypertension, CVD, and cancer, and a higher likelihood of exposure to nonsteroidal anti-inflammatory drugs (NSAIDs) or contrast." (PMID 33846379, 2021). "Older age, diabetes, cerebrovascular disease, worse renal function, lower levels of hemoglobin and albumin, CPB, prolonged operation time, large bleeding volume, and ultrafiltration volume might increase the hazard of CSA-AKI." (PMID 33937278, 2021). "The recent 2020 KDIGO guidelines supports this approach in a more general sense as they recommend multifactorial diabetes management with yearly assessment of urine albumin excretion and eGFR, but refer to primary care and endocrinology society guidelines for further details." (PMID 34011313, 2021). "Next, we explored possible risk factors for lymphopenia in the pretreatment patient characteristics, including age, sex, performance status, BMI, clinical TNM staging, clinical stage, tumor location, diabetes mellitus, hemoglobin, albumin, lymphocytes, and WBC." (PMID 34514723, 2021). "Compared to patients who underwent cardiac surgery after 7 days, those who had surgery within 7 days of CAG had fewer comorbidities such as hypertension, diabetes mellitus, and cerebrovascular disease and had a higher ejection fraction, albumin level, and hematocrit value." (PMID 33937278, 2021). "The baseline characteristics of gender (p=0.425), diabetes mellitus (p=0.13), hypertension (p=0.104), cardiac failure (p=1.0), albumin (p=0.13), alcohol (p=0.587), and smoking status (p=0.977) were not significantly different between the patients who progressed and those who did not." (PMID 33877260, 2021). "The inverse association of albumin with hs-CRP is consistent with the anti-inflammatory properties of albumin and its consumption with chronic inflammation, that may complicate the clinical course of diabetes." (PMID 34239442, 2021). "A comparison of diabetes risk factors between the groups showed that individuals with diabetes were more likely to be hypercholesterolemic compared with individually matched controls, and had significantly higher LDL-C, TC, and urine albumin levels." (PMID 35069433, 2021). "However, the two groups were similar in age, height, body weight, the BMI, NRS-2002 score, presence of hypertension, presence of diabetes mellitus, and levels of hemoglobin, albumin, and other indicators (all p > 0.05)." (PMID 34912839, 2021). "Models were adjusted for sex, age, ethnicity, ratio of family income to poverty, education level, BMI, drinking history, smoking history, vitamin D supplements, physical activity, protein intake, serum albumin, heart disease, stroke, hypertension, and diabetes." (PMID 35242790, 2021). "It was found that the association between albumin and HbA1c was strongest in HbA1c-defined diabetes, with a curve and threshold, and the negative correlation was significantly stronger at levels below 41.4 g/L." (PMID 34055818, 2021). "Moreover, a clinical study demonstrated that zinc supplementation reduces urinary albumin excretion in patients with type 2 diabetes mellitus (DM) with microalbuminuria." (PMID 33974681, 2021). "The most common include older age, low serum albumin, immunosuppression and diabetes." (PMID 35011801, 2021).
diabetes (continued). "Contrary to formerly reported positive relations between serum ferritin and proteinuria, we found a negative association between HIC and urine albumin in men when including participants with established diabetes in the analysis." (PMID 34940629, 2021). "The results remained stable after adjustment for sex, age, ethnicity, ratio of family income to poverty, education level, BMI, alcohol consumption, smoking history, vitamin D supplements, protein intake, serum albumin, heart disease, stroke, hypertension, and diabetes." (PMID 35242790, 2021). "For CV mortality, we adjusted age, diabetes, albumin, and triglycerides." (PMID 33390774, 2021). "Urinary albumin excretion was also increased from 12 to 16 weeks after the onset of diabetes." (PMID 33947045, 2021). "In findings obtained with multivariate Cox proportional hazards analysis after adjusting for age, gender, albumin, diabetes, hypertension, and history of CVD, the adjusted HR value was 0.40 (95% CI 0.17–0.90; p = 0.027), above the median value for the higher fat tissue index group." (PMID 34072922, 2021). "Univariate Cox proportional hazard analysis regarding prediction of cardiac death revealed that SAS score, presence of progressive AS, history of diabetes, history of ischemic heart disease, and serum levels of albumin and C-reactive protein were significant independent variables." (PMID 34513029, 2021). "Considering the strong correlation between WBC and NLR, we assessed factors associated with WBC and found that WBC was positively correlated with NLR, HbA1c, TC, TGs, LDL-c, and UA and negatively correlated with ALB after adjustment for age and duration of diabetes." (PMID 35071771, 2021). "However, at present, a serum albumin-based delivery solution has been developed for diabetes and HIV." (PMID 34771316, 2021). "The risk of TB infection was highest in patients with CKD stage 5, followed by patients with CKD stage 4, stage 3, stage 2, and the risk were lowest in patients with CKD stage 1 (p < 0.01) with adjustment for patients' age, gender, BMI, diabetes, liver cirrhosis, calcium, and albumin." (PMID 34485344, 2021). "Moreover, serum albumin levels significantly affected the odds ratios of the HbA1c thresholds that are commonly employed for diagnosis and management of diabetes." (PMID 34055818, 2021). "Oxidative modifications of serum albumin Cys34 have previously been investigated in various disease states, such as organ failure, kidney diseases, and diabetes mellitus, where increased percentages of reversibly and irreversibly oxidised plasma albumin Cys34 are reported and exercise." (PMID 34439489, 2021). "PhenoAgeAccel PRS was more strongly associated than BioAgeAccel PRS with liver and kidney diseases and the associated biomarkers, for example, albumin, total bilirubin, creatinine, and cystatin C, plus COPD, hypothyroidism, type I and type II diabetes, and rheumatoid arthritis." (PMID 34038024, 2021). "Nevertheless, patients with small kidney size were not only older (P = 0.007), suffered longer duration of diabetes mellitus (P = 0.006), but also had lower serum levels of creatinine (P = 0.022) and albumin (P = 0.010) than patients with enlarged or normal kidney size." (PMID 33859292, 2021). "However, at 24 weeks post diabetes induction, average urine albumin levels were significantly increased in WT-STZ mice compared to nondiabetic controls and this was significantly attenuated in miR-379KO-STZ mice." (PMID 33398021, 2021). "A systematic review also found significant benefits of high-flux dialyzers on all-cause mortality for certain pre-specified conditions, such as a serum albumin level <4 g/dL, a maintenance hemodialysis duration >3.7 years, and presence of diabetes or arteriovenous fistula." (PMID 34513892, 2021).
diabetes (continued). "The least absolute shrinkage and selection operator (LASSO) regression, univariate and multivariate Cox regression analysis revealed that serum albumin and lymphocyte count were independent protective factors while CA19-9 and diabetes were independent risk factors." (PMID 34136406, 2021). "The likelihood of receiving a kidney transplant was compared between HD and HDF, and evaluated across different subgroups: age, sex, diabetes, history of cardiovascular disease, albumin, dialysis vintage, fistula, and level of convection volume standardized to body surface area." (PMID 33632160, 2021). "In addition, patients with diabetes had marginally reduced hemoglobin and albumin levels and increased leukocyte counts compared to patients without diabetes (p = 0.05, p = 0.05, and p = 0.07, respectively)." (PMID 33506050, 2021). "In addition, old age, diabetes, a low level of albumin, high level of triglycerides, and high usage of calcium channel blockers were associated with increased CV mortality." (PMID 33390774, 2021). "The data allowed us to build models that could distinguish DKD from diabetes (AUC = 0.928) with 2 proteins (ALB, AFM), and distinguish DKD3 from DKD4 (AUC = 0.949) with 3 proteins (ANXA7, APOD, C9)." (PMID 34963468, 2021). "Among these factors, age was the strongest predictor of sarcopenia [age group over 70 years old, odds ratio (OR), 7.20; 95% confidence intervals (CIs), 2.09–24.79, P = 0.002] after adjusting for sex, BMI, diabetes, hypertension, eGFR, serum albumin level, and hemoglobin." (PMID 34531464, 2021). "Increases in oxidized ALB have been observed in patients with liver disease, renal failures, diabetes mellitus, and hypertension, in subjects after strenuous exercise, and in aged population; all of these have exclusively been viewed as the manifestation of oxidative stress." (PMID 33804859, 2021). "In addition, albumin levels were decreased by diabetes induction and treatment with the aqueous extract of fenugreek and buckthorn." (PMID 34497854, 2021). "Their random survival forest model for time to microalbuminuria based on six variables—HbA1c, marital status, urine albumin value, insulin regime, degree of retinopathy, postpubescent diabetes duration, and weight—had a concordance level of 0.82 on a test data set." (PMID 34769614, 2021). "According to Strategy II for adjusting confounding variables, in addition to gender and age, we also adjusted variables selected in the covariate screening, including history of smoking, diabetes mellitus, heart rate at admission, serum albumin, CK, CK-MB, uric acid, PT, and D-dimer." (PMID 33573626, 2021). "Another factor influencing the Cu/Zn ratio is hormone signaling, particularly the decline of insulin, GH, and IGF-1, which are all stimulators of albumin synthesis, and this decline is common in elderly or pathological conditions such as diabetes or pre-diabetes." (PMID 34066564, 2021). "Additionally, decreased serum albumin, liver malfunction, diabetes, and corticosteroid therapy are attributed to decreased vitamin D levels post-transplantation." (PMID 33801744, 2021). "Moreover, since CKD is frequent in patients with diabetes mellitus, attention has been focused on albumin glycation; however, other modifications, such as albumin oxidation, have been less considered." (PMID 33800425, 2021). "Glycated albumin (GA) is an important glycemic control marker for diabetes mellitus." (PMID 33572552, 2021). "Moreover, given that albumin is characterized by easy aggregation and change in structure, there is a great chance of modification and polymerization in people with diabetes or other diseases." (PMID 34055818, 2021). "Statistical analysis revealed a variety of factors, including low postoperative albumin, tumor close to the anus, diabetes, perioperative blood transfusion, diarrhea, later tumor stage, and high score of PG-SGA, which can lead to AL; these factors in the previous literature have also been confirmed." (PMID 32461995, 2020).
diabetes (continued). "Therefore, the purpose of this work is to evaluate the effect of a mixture of fatty acids (FA) with different saturated and unsaturated acids on the affinity of acetohexamide (AH) for glycated albumin, simulating the state of diabetes in the body." (PMID 32429512, 2020). "In addition, the use of in vitro-glycated albumin confirms the specific role of AGEs, generated both in vitro and in vivo, in the diabetes mellitus milieu." (PMID 33019603, 2020). "Using peritonitis as the dependent variable, the following variables were included as covariates, to establish a binary logistic regression model: age, gender, diabetes mellitus, hemoglobin, albumin, serum creatinine, cholesterol, potassium, c-reactive protein (CRP), and season." (PMID 32781861, 2020). "Of note, targeting albumin or using albumin-fusion technology is also used in the case of coagulation factor IX for the treatment of hemophilia B, as well as for biotherapeutics for the treatment of diabetes, cancer or rheumatoid arthritis." (PMID 32477339, 2020). "To evaluate whether cyclin G2 protects against renal dysfunction developed in diabetes, we assessed blood glucose, 24‐hour urinary albumin, urinary creatinine, body weight and kidney weight in our animal model." (PMID 31978940, 2020). "Finally, meta-analyses supported that sulodexide treatment was associated with a higher proportion of patients that achieved at least a 50% decrease in albumin excretion rate with diabetes and micro- and macroalbuminuria (odds ratio 3.28 (95% CI 1.34-8.06))." (PMID 32851094, 2020). "In addition, the correlation between the T-AN level and eGFR and between the H-AN level and eGFR were stronger than that of the albumin level and eGFR especially in patients with diabetes." (PMID 32985540, 2020). "Correlation analysis revealed that levels of sIL-2R were positively correlated with age, presence of diabetes, hepatitis-seropositive status, monocyte count, as well as hsCRP, β2-MG, and NT-proBNP levels, whereas negatively correlated with hemoglobin, albumin, SCr, and HDL-C levels." (PMID 32401100, 2020). "Systolic and diastolic BP values, serum levels of total cholesterol, triglycerides, glucose, and creatinine, albumin/creatinine ratio, and the prevalence of male sex, hypertension, diabetes mellitus, dyslipidaemia, obesity, and proteinuria significantly increased with increasing AIP quartiles." (PMID 32815171, 2020). "Regarding the risk factors associated with survival, age, diabetes, serum albumin, BMI, and cardiovascular disease were not consistent with our results." (PMID 32972378, 2020). "This indicates that in the long term, patients with ESKD who have also developed diabetes may exhibit decreasing albumin levels because of the comorbidity." (PMID 32295526, 2020). "Additionally, they exhibited lower levels of eGFR, serum albumin and hemoglobin but a higher proportion of hypertension, diabetes, hyperuricemia and hyperlipidemia." (PMID 32469090, 2020). "In univariable analysis, age, male sex, body mass index, category of operation, dysrhythmia, pulmonary hypertension, malignancy, diabetes, ASA classification, hemoglobin levels, albumin levels and bis40map50_dur were found to be potential risk factors for 180-day mortality." (PMID 32795266, 2020). "We also separately analyzed the demographic details of each one of the 6 recurrent DVT patients in rivaroxaban arm and found that 4 of 6 had gastric or pancreatic cancer, low albumin, BMI less than 22 and shared co-morbid (Diabetes, Hypertension and Coronary Artery Disease)." (PMID 32489329, 2020). "Besides, albumin decreased significantly in diabetes, indicating that the basic condition of diabetic patients was poor." (PMID 33382747, 2020).
diabetes (continued). "Measurements by MIP sensors in real biological samples, e.g., blood, are still complicated by the presence of highly abundant proteins in the g/L region, e.g., serum albumin and immunoglobulin, while protein markers for cancer, diabetes or heart failure are typically in the mg/L to ng/L range." (PMID 32397160, 2020). "Poor prognostic factors for improvement were older age, poor handgrip strength, weight loss, poor physical activity, hospitalizations, previous cancer or stroke, lung disease, lower cognitive function, diabetes, osteoarthritis, low albumin levels and high IL-6 levels." (PMID 33193369, 2020). "To this end, we constructed regression tree models using the CART algorithm in the phase II (unmatched) population including the variables that composed the AURORA Risk Score 24: age, albumin, hsCRP, history of CVD and history of diabetes, in addition to the three candidates." (PMID 32754270, 2020). "Cases had lower body mass index, albumin and prealbumin, and significantly higher odds ratios for diabetes, hypertension, cardiovascular and peripheral vascular diseases, chronic kidney disease, liver disease, malignancy, osteoporosis and fractures (all p < 0.05)." (PMID 32736613, 2020). "Age, dialysis vintage, serum albumin, comorbidity index, and diabetes did not significantly affect LTM loss over time." (PMID 32824951, 2020). "ADA and JNC 8 equally recommend the prescription of an angiotensin-converting enzyme inhibitor (ACEI) or angiotensin II receptor blocker (ARB) for hypertensive patients with type 2 diabetes mellitus (T2DM) with overt proteinuria (urine albumin to creatinine ratio (UACR) ≥ 300 mg/g creatinine)." (PMID 32802494, 2020). "Other mortality predictors included older age, history of CVD, diabetes mellitus, lower serum level of albumin, prealbumin, urea nitrogen, creatinine, uric acid and increased serum level of high sensitivity-C reactive protein, soluble interleukin-2 receptor, N-terminal pro-brain natriuretic peptide." (PMID 32660510, 2020). "Administration of apigenin reduced the CD38 expression and mitochondrial oxidative stress in diabetic kidneys, resulting in improved diabetes-induced renal injuries, such as tubulointerstitial fibrosis, tubular damage, inflammation, and urinary albumin/L-FABP excretion." (PMID 32507768, 2020). "Gait speed and handgrip strength showed very weak correlations with different determining factors (older age, the presence of diabetes, and lower serum albumin level for low gait speed, and lower body mass index and the presence of previous cardiovascular events for low handgrip strength)." (PMID 32375664, 2020). "After adjustment for age, gender, urine albumin/creatinine ratio, diabetes, BMI, CRP, WHR, alcohol consumption, cholesterol and triglycerides, low serum albumin (p < 0.001), haemoglobin (p = 0.012) and bilirubin (p = 0.011) were associated with annual decline in eGFR." (PMID 33261565, 2020). "These vitro glycation models appeared relevant to what could be encountered in vivo as most of oxidative damages, identified in our in vitro glycated albumin and erythrocytes preparations, were retrieved in albumin and erythrocytes isolated from diabetics." (PMID 32408712, 2020). "In addition, we found significant differences between older and younger patients in many clinical parameters, including serum albumin, eGFR, and nephrotic-range proteinuria, as well as comorbidities, such as hypertension and diabetes." (PMID 33035278, 2020). "Patients in the low expression group had significantly longer diabetes disease course, higher HbA1c levels, lower plasma ALB levels, lower eGFR, higher 24 h urinary protein quantity, higher SCr, and higher urinary PCR/UCr ratio than patients in the high expression group (all P < 0.01)." (PMID 32337271, 2020).